SLPI (secretory leukocyte peptidase inhibitor)
Diseases named in the same sentence as SLPI in open-access papers (continued):
Sharing a sentence is not in itself a finding about the gene and the disease.
bacterial infections (10 papers, 2012 to 2025). "It is unclear what predisposes patients with COPD to secondary bacterial infections, although it has been suggested that observed reductions in levels of the antibacterial peptides secretory leukocyte protease inhibitor (SLPI) and elafin in COPD patients may contribute." (PMID 35563722, 2022). "SLPI, coexpressed with DMBT1 (coexpression score 0.078 from the GEO database, STRING), modulates inflammatory responses after bacterial infection, while OLFMA4 and SCGB1A1 are also associated with salivary gland function." (PMID 39580055, 2024). "The PM also serves as a barrier to bacterial infection during gestation, containing layers of antimicrobial peptides, such as human defensins, elafin, secretory leukocyte protease inhibitor (SLPI), and histones H2A and H2B." (PMID 35496035, 2022). "The secretory leukocyte protease inhibitor (SLPI) is a serine protease inhibitor which plays important role in bacterial infection, inflammation, wound healing and epithelial proliferation." (PMID 32742768, 2020). "SLPI is noticed for versatile immunological functions, and our results warrant further studies that elucidate the role of SLPI in severe bacterial infections." (PMID 31089838, 2019). "FP also suppressed RV induction of secretory leukoprotease inhibitor (SLPI) protein (~50% reduction), an antimicrobial peptide (AMP) implicated in protection against secondary bacterial infection following RV infection in COPD14." (PMID 29884817, 2018). "In human UEC estradiol stimulates the production of antimicrobial compounds such as elafin and secretory leukocyte protease inhibitor (SLPI) that are essential in restricting viral and bacterial infections." (PMID 22558189, 2012).
inflammation (3 papers, 2021 to 2025). Aberrant reaction of the microcirculation characterized by movement of fluid and leukocytes from the blood into extravascular tissues. "UPEC-infected SLPI-deficient (Slpi−/−) mice suffer from higher urine bacterial burdens, prolonged bladder inflammation, and elevated urine neutrophil elastase (NE) levels compared to wild-type (Slpi+/+) controls." (PMID 38270443, 2024). "Here, we show a possible pathomechanism between ELANE mutation, diminished NE and SLPI expression, and dental inflammation in ELANE dental pulp cells." (PMID 34580954, 2021). "Furthermore, two treatment models using SLPI KO mice, administration of a serine protease inhibitor, bovine pancreatic trypsin inhibitor, or anti-IL-33 antibody, attenuated Th2 airway inflammation." (PMID 40546642, 2025).
benign tumors (2 papers, 2009 to 2017). "Differential expression was also observed between LMP tumors and benign tumors/normal ovaries for three out of five genes examined (PDGFRA, SLPI, WNT7A) and between invasive and LMP tumors for the other two genes (C6orf31, GLTSCR2) (Kruskal Wallis p < 0.05)." (PMID 19849863, 2009).
cardiovascular diseases (2 papers, 2022). "However, overexpression of SLPI in cardiovascular diseases has only been investigated in an in vitro experiment." (PMID 36061560, 2022). "However, overexpression of SLPI gene in cardiovascular diseases has only been investigated in an in vitro experiment." (PMID 36061560, 2022). "Nonetheless, anti-protease activity deficient SLPI has never been investigated with cardiovascular diseases, particularly myocardial ischaemia/reperfusion injury." (PMID 35625725, 2022).
metabolic disorders (1 paper, 2024). "Given the increased chronic stress and inflammation in DKD, it is tempting to speculate that the upregulation of circulating SLPI may be associated with metabolic disorders to meet the demands of anti-stress and anti-inflammatory activities." (PMID 38501106, 2024).
SLPI also shares sentences with these, for which no sentence is quoted: nasopharyngeal carcinoma (4 papers); bladder cancer (3); bladder tumors (3); Autoimmunity (2); gingivitis (2); glioblastoma (2); ichthyosis (2); infectious disease (2); lymphoma (2); non-small cell lung carcinoma (2); acute respiratory distress syndrome (1); autoimmune hepatitis (1); benign prostatic hyperplasia (1); brain tumors (1); breast invasive carcinoma (1); bronchiolitis obliterans (1); bronchopulmonary dysplasia (1); Cerebral ischemia (1); chronic hepatitis B infection (1); chronic periodontitis (1); co-infection (1); colorectal adenocarcinoma (1); dermatitis (1); eosinophilic granulomatosis with polyangiitis (1); fibrosis (1); gastrointestinal tumors (1); glomerulonephritis (1); head and neck tumor (1); Hypertension (1); kidney disease (1).
A further 19 diseases each share a sentence with SLPI in 1 paper.